CXCL1 (C-X-C motif chemokine ligand 1)
Diseases named in the same sentence as CXCL1 in open-access papers (continued):
Sharing a sentence is not in itself a finding about the gene and the disease.
tumor (continued). "Patient‐specific analysis of amplitude and duration of cytokine and chemokine persistence in CSF of humans after SCI revealed that proinflammatory chemokines CXCL1 and CCL3 tend to positively correlate with length of tumor, whereas anti‐inflammatory cytokine IL‐10 correlates negatively." (PMID 41147460, 2026). "Indeed, macrophage depletion via anti-CSF1R mAb or clodronate liposomes significantly decreased the number of cells expressing CXCL1/2 and CFB in tumor, as well as the levels of C3a and C5a." (PMID 41480760, 2026). "In addition, the levels of CXCL1, CXCL8, VEGFA, and VEGFB related to monocyte recruitment and angiogenesis were higher in patients with advanced stages than in those with tumor stage 1." (PMID 40860188, 2025). "Furthermore, METTL14 modulates the expression of various chemokines (e.g., CXCL1, CCL2), which promote the expansion of immune-suppressive cells within the tumor microenvironment." (PMID 39911396, 2025). "In the early stages of tumor progression, the presence of cDC1s in the TME is limited due to the preferential recruitment of tumor‐promoting immune cells by chemokines such as C‐X‐C motif chemokine ligand 1 (CXCL1), C‐C motif chemokine ligand 2 (CCL2), and CCL20, which are secreted by tumor cells." (PMID 40667699, 2025). "Moreover, Non-Responders exhibited upregulation of chemokines including CXCL1 and CXCL8 and enrichment of immunoregulatory M2 macrophages in tumor regions, suggesting active macrophage recruitment from the stroma." (PMID 41388608, 2025). "In addition, G31P-mediated CXCR1/2 inhibition disrupts the pathological feedback loop in the tumor microenvironment, where ELR+ CXC chemokines (CXCL1/8) activate CXCL8, leading to EGFR transactivation and sustained inflammatory signaling." (PMID 41425704, 2025). "Targeting the MAGEA6/YY1/CXCL1‐SC axis may provide a promising strategy to inhibit PNI and tumor progression, ultimately improving patient prognosis." (PMID 40145793, 2025). "Genes Ptgs2, Cxcl1, Vegfa, Cxcl2, Col1a1 and Col1a2 were downregulated in cluster 0 of the A101 CAR-T-treated tumor compared to the mock-T-treated group which are involved in angiogenesis and tumor-promoting inflammation as well as EMT and tumor progression." (PMID 40568084, 2025). "Intermittent hypoxia activates the NF-κB/HIF-1α pathway, increasing pro-inflammatory mediators like COX-2, CCL2, CXCL1, PGE2, and CSF1, these mediators recruit monocytes and neutrophils to the tumor microenvironment (TME), differentiating into TAMs and Tumor-Associated Neutrophils (TAN)." (PMID 41357522, 2025). "Therefore, ERO1α+ tumor cells secrete G-CSF, which acts as a proliferation factor for PMN-MDSC cells as well as CXCL1 and CXCL2, which stimulate PMN-MDSC cells recruitment from the circulation into the tumor stroma." (PMID 41226317, 2025). "In the context of tumourigenesis, cells within the tumour ecosystem produce cytokines, chemokines, growth factors, and other molecules, such as TGF-β, monocyte chemoattractant protein 1, IL-6 and IL-8, Tumour Necrosis Factor TNF-β, CXCL-1, and VEGF." (PMID 41009413, 2025). "It has been reported that depression promotes tumor growth and metastasis by affecting TAM/CXCL1 in the tumor microenvironment, but the downstream receptors of CXCL1 (such as CXCR1/CXCR2) have not been investigated in these studies." (PMID 40839237, 2025). "Beyond its direct effects on cancer cells, CXCL1 influences the tumor microenvironment by acting on non-malignant cells." (PMID 40427171, 2025). "Specifically, the detection of the species Fusobacterium nucleatum, a constituent of this phylum, has been linked to increased expression of pro-inflammatory chemokines such as CXCL1, CXCL2, and CCL2, alongside enhanced angiogenesis and tumour gene expression alterations." (PMID 41516317, 2025).
tumor (continued). "CXCR2 ligands such as CXCL1, CXCL2, CXCL3, and CXCL5 are highly expressed in the tumor microenvironment of KRAS-mutant preclinical models, although their elevated secretion is often attributed to stromal or immune cells rather than direct production by KRAS-mutant tumor cells." (PMID 40524071, 2025). "Moreover, besides G-CSF there are other cytokines such as CXCL1 and CXCL2, which are also known for their ability to recruit PMN-MDSC cells from the circulation into the tumor stroma." (PMID 41226317, 2025). "While the full MAC assembly can cause cell lysis, sub-lytic MAC deposition—facilitated by elevated C7—activates intracellular pathways in tumor cells, including Ca2+- and G-protein-mediated signals, and transcription factors such as EGR1, IRF1, AREG, and CXCL1." (PMID 40806542, 2025). "MAGEA6 interacts with the transcription factor Yin‐Yang 1 (YY1), which subsequently increases the secretion of CXCL1 by CRC cells, facilitates the recruitment of CRC cells to SCs, while also enhancing tumor cell invasiveness through epithelial‐mesenchymal transition (EMT), ultimately promoting PNI." (PMID 40145793, 2025). "CSCs activate the expression of the chemokines CXCL1, CXCL2, and CXCL8 through the ERK pathway, facilitating the recruitment of MDSCs within the tumor, whereas MDSCs help maintain the stem cell characteristics of cancer cells, promote angiogenesis, and assist in CSC metastasis and colonization." (PMID 41368628, 2025). "Notably, members of the CXC chemokine family, including CXCL1, CXCL2, CXCL3, CXCL5 and CXCL8, function through the activation of CXCR1 and CXCR2, playing a key role in promoting tumour angiogenesis." (PMID 39161078, 2025). "Specifically, PKM2-induced CXCL1 and MIF produced by tumor cells can bind to CXCR2 and CXCR4 receptors on MDSCs, thereby activating the signaling pathway of MDSCs and triggering cytoskeletal rearrangement, which makes MDSCs chemotactic to the periphery of tumor cells." (PMID 40948745, 2025). "Investigations into how p38 may regulate the expansion and recruitment of TAMs and MDSCs showed that p38α controls the tumor cell expression of cytokines and chemokines (e.g., CCL2, CXCL1, IL6, GM-CSF, G-CSF)." (PMID 41282257, 2025). "Due to increased CXCL1 expression in many cancers, CXCR2 transduction into lymphocytes increases tumor infiltration by such modified cells, which was confirmed by experiments on T cells with increased CXCR2 expression, which specifically migrated to ovarian cells." (PMID 40427171, 2025). "Some mediators involved in communication between tumour cells and CAFs—such as BMP-4, IGF-2, IL-6, IL-8, CXCL-1, and TGF-β—may be potential therapeutic targets." (PMID 41009413, 2025). "CAF release of chemokine (C-X-C motif) ligand 1 and 2 (CXCL1 and CXCL2) also increases tumor invasion, with CXCL12 further increasing macrophage recruitment, and CXCL1 increasing tumor invasion via activation of matrix-metallopeptidase 1 (MMP1), also known as interstitial collagenase." (PMID 40872475, 2025). "Compared with control, Vox led to a slight decrease (not significant) of Cxcl1 expression in cancer cells, to a strong downregulation of Cxcl5 in total immune cells and macrophages, and to a modest upregulation of Cxcl2 in tumor macrophages." (PMID 40139833, 2025). "Plasma CXCL1 levels fail to be a biomarker; however, our results confirmed that tumor-derived STK11 plays a pivotal role in regulating cytokine secretion, thereby contributing to the modulation of the tumor–immune microenvironment." (PMID 41051525, 2025). "CXCL1 and the broader CXCR2 axis play a key role in tumor progression." (PMID 40427171, 2025). "Among them, the chemokine family, including CC (e.g., CCL1, CCL3, CCL5, CCL7, and CCL15), CXC (e.g., CXCL1, CXCL3, CXCL5, and CXCL10), XC (e.g., XCL1 and XCL2), and CX3C (e.g., CX3CL1), plays a pivotal role in tumor development, metastasis, and chemotherapy resistance 30-33." (PMID 40740234, 2025).
tumor (continued). "TGF-β further polarizes TANs to the pro-tumor N2 phenotype, whereas blocking TGF-βpromotes the accumulation of N1-TANs and upregulates chemotaxis/adherence and cytotoxic-related programs (such as CXCL1/2/5, ICAM-1), synergizing with CD8+ T cells to suppress tumor growth." (PMID 41473772, 2025). "Additionally, chemokines such as CXCL1, CXCL2, CXCL5, CCL2, and CCL3, produced by MAFs, play a role in attracting pro-tumor MDSCs to inhibit CD8+ cells." (PMID 40136652, 2025). "Additionally, CXCL1 and PAI-1 were analyzed due to their roles in enhancing tumor cell survival, invasion, and resistance to apoptosis." (PMID 40652770, 2025). "Aging immune cells also promote tumor metabolic reprogramming via cytokines and secreted factors: Senescent immune or stromal cells secrete pro-inflammatory SASP factors (e.g., IL-6, IL-8, TNF-α, CXCL1), activating STAT3 and NF-κB pathways in tumor cells." (PMID 40881346, 2025). "Although senkyunolide H did not reduce the infiltration level of tumor CXCL1, it significantly inhibited the activation of the PI3K/AKT signaling pathway induced by CUMS." (PMID 40839237, 2025). "GPR35 contributes to tumor cell metabolism by interacting with the α-subunit of the Na+/K+-ATPase, activating Src kinase signaling, and promoting the secretion of the neoangiogenic factors such as VEGF and CXCL1." (PMID 41459506, 2025). "In the tumor microenvironment, PKM2 promotes tumor cells to release cytokines and aggregates a large number of MDSCs around tumor cells, PKM2 facilitates the binding of cytokines, such as CXCL1 and MIF, released by tumor cells to the surface receptors CXCR2 or CXCR4 on MDSCs." (PMID 40948745, 2025). "In tumor biology, interleukins as IL-1b, IL-8, IL-6 promote cell proliferation and epithelial-mesenchymal transition (EMT), but IL-6 also influences cell cycle arrest and immune clearance of damaged cells, as well as CCL2 and CXCL1." (PMID 38175424, 2024). "Mechanistically, metformin inhibited CXCL1 secretion in ESCC cells and tumor xenografts." (PMID 38474224, 2024). "Tumor-educated MSCs can further activate and release the chemoprotective and immunomodulatory factors including CXCL1, CXCL2, and IL-8, favoring tumor progression in which MSCs generated CXCL2, VEGF, TGF-β, and IL-6 can further raise tumor aggressive phenotype by boosting tumor angiogenesis." (PMID 38951845, 2024). "As a tumor cell-intrinsic regulator, non-inflamed tumor-derived CXCL1 signaled to increase the infiltration of MDSCs and simultaneously expels DCs and T cells, driving resistance to immunotherapy." (PMID 39107856, 2024). "Moreover, another study has suggested that the overexpression of CXCL1 and CXCR2 has a positive effect on tumor growth by recruiting Tregs." (PMID 38515216, 2024). "Moreover, colorectal CSCs secreted CXCL1/2, which recruited CXCR2-expressing neutrophils from the bone marrow to the tumor niche." (PMID 38254219, 2024). "The comparison of tumor tissue (TU) and adenomatous polyp tissue (TU) highlights that the expression of CXCL1, CXCL8, and PTGS2 does not differ significantly (adj." (PMID 38979413, 2024). "Furthermore, CXCL1 and CXCL8 expression in adenomatous polyps reached levels comparable to those observed in tumor tissues." (PMID 38979413, 2024). "MDSCs express several chemokine receptors such as CCR2, CXCR2, CXCR4, and CXCR5, while liver tumor cells or malignant hepatocytes express chemokines such as CCL2, CCL5, CXCL1, CXCL5, and CXCL12, and the chemokine/its receptor axis mediates MDSC infiltration in the tumor microenvironment." (PMID 38397901, 2024). "Consequently, strategies aimed at modulating the activity of CXCL1, CXCL5, and CXCL8 hold promise as potential therapeutic interventions to impede tumor angiogenesis." (PMID 38047300, 2024). "Likewise, tumor cells and tumor-infiltrating CD11b+ myeloid cells can contribute to the high expression of CXCL1 and CXCL2, and deletion of CXCL1 and CXCL2 delays in vivo tumor growth." (PMID 39621069, 2024).
tumor (continued). "Subsequently, CXCL1/CXCL2 recruits MDSCs, which suppress the activity of tumor-specific T cells." (PMID 38254219, 2024). "Some studies have demonstrated that by inducing the Warburg effect in the tumor microenvironment (TME), activated C-X-C motif chemokine ligand 1/2 (CXCL1/2) binds to C-X-C motif chemokine receptor 2 (CXCR2), recruiting MDSCs and other cells, thereby fostering tumor growth and immune escape." (PMID 39192979, 2024). "They revealed a “cell-autonomous” interaction of CXCL1 with CXCR2+ neutrophils, and silencing CXCL1 reprogrammed the trafficking and functional dynamics of neutrophils to overcome T cell exclusion and control tumor growth in a T cell-dependent manner." (PMID 38982491, 2024). "A prior investigation showed that the overexpression of CXCL1 and CXCL2 by interleukin 6 can enhance the recruitment of monocytes and drive macrophages towards a protumor phenotype, ultimately leading to the formation of a suppressive tumor microenvironment." (PMID 38214842, 2024). "The expression levels of ccl-2 (MCP-1), ccl-20 (MIP-3), ccl-7 (MCP-3), CXCL-4 (PF-4), CXCL 1 (Gro -), and CXCL-12 (SDF-1) are also significantly increased in replicative senescent cells, allowing the disruption of the blood-tumor barrier integrity and greater spread of tumor cells." (PMID 37450933, 2024). "Mice with TKTB6-RAS–derived tumors, which grew relatively slower than TKTB34-RAS–derived tumor, owing to lower HRASG12V expression levels, demonstrated elevated CXCL1 levels suggesting a correlation between circulating CXCL1 and mutant RAS-induced skeletal muscle defect." (PMID 38651826, 2024). "Tumor tissues expressed more chemokine genes (CXCL1/3/8) than normal tissues with the exception of the breast tissue." (PMID 38744958, 2024). "The qRT-PCR results showed that CXCL1, PIGR, and TNFRSF14 were significantly lower expressed in BC tissues than adjacent tissue, while CXCL13 and NKAIN were significantly upregulated in BC tissues compared with adjacent tumor tissue." (PMID 39287311, 2024). "Finally, these findings contribute significantly to our understanding of the role of CXCL1 as a critical factor in ERBC tumor growth and metastasis via crosstalk with fibroblast in tumor microenvironment." (PMID 38393465, 2024). "Subclusters 4 and 5 may be related to tumor invasion and metastasis (migration factors CXCL3 and CXCL1; adhesion factors CEACAM6 and EMP1), suggesting that they may be tumor cell clusters with a greater degree of malignancy." (PMID 38927691, 2024). "CXCL1 plays a dual role by facilitating the recruitment of TANs, thereby promoting tumor growth and diminishing the CD8+ T cell population, weakening the immune defense against the tumor." (PMID 38791111, 2024). "Both CXCL1 and CXCL3 genes, along with CCL22, are involved in the chemotaxis of tumor cells and stromal cells within the surrounding microenvironment, which is essential in tumor dissemination during progression and metastasis." (PMID 39408697, 2024). "However, after cessation of treatment, neutrophils are recruited to the metastatic liver via CXCL1 and CXCL2 secreted by metastatic tumor cells." (PMID 38167055, 2024). "Previous study showed that CAFs could mediate resistance to CSF-1R therapy by secreting CXCL1 and CXCL2 to recruit PMN-MDSCs, and the combined inhibition of CXCR2 and CSF-1R could overcome tumor resistance." (PMID 38291516, 2024). "We treated ER+ tumor cells (MCF7) with fulvestrant in the presence or absence of the top five secreted cytokines (GROα/CXCL1, IL-8, CXCL5, hepatocyte growth factor (HGF) and CCL19)." (PMID 37423299, 2023). "Consistent with previous results, Phgdh without NLS1 lost its pro‐tumor functions in both tumor volume and Cxcl1/Il8 expression." (PMID 37078828, 2023).
tumor (continued). "Pharmacological targeting of neutrophils and their chemokine receptor CXCR2, or genetic ablation of the neutrophil recruiting chemokine Cxcl1, results in extended survival of PDGFB-driven tumor-bearing qMCP-deficient mice but not WT tumor-bearing mice." (PMID 37012245, 2023). "Our findings that SERPINB3 modulated the crosstalk between immune cells and cancer cells via secretion of CXCL1/8 and S100A8/A9 implicate this protease inhibitor member of the SERPIN superfamily in a key tumor strategy of evading antitumor immune responses and resisting therapies such as radiation." (PMID 37279067, 2023). "Since the secretion of CXCL1 and CXCL8 by cancer cells promoted TANs recruitment to the tumor sites, we hypothesized that ETV4 might promote TANs accumulation." (PMID 36670069, 2023). "Moreover, it was shown that primary tumor cells (of colorectal carcinoma) secrete VEGF-A, stimulating TAMs to produce CXCL1, which recruits CXCR2+ MDSCs to form a pre-metastatic niche that promotes liver metastasis." (PMID 36260158, 2023). "Therefore, our study further established the bridge between the brain, tumor, and spleen via GC/GR-TAM/CXCL1-MDSC signaling." (PMID 37210553, 2023). "This resulted in activation of tumour‐promoting cytokines (IL‐6, IL‐8, MCP‐1 and CXCL1)." (PMID 37759347, 2023). "Thus, IL-17 stimulates the production of CXCL1/CXCL5/Granulocyte Colony-Stimulating Factor (G-CSF) by ASCs and other cells present in the tumor microenvironment." (PMID 36766689, 2023). "After anti-HER2 treatment, in tumours exhibiting HER2 amplification, there would be a downregulation in the release of cytokines, including CCL2, CCL21, VEGF, and CXCL1, which leads to an amelioration of the immunosuppressive factors within the tumour microenvironment." (PMID 37720943, 2023). "We also observed that MDSC-secreted VEGFA and multiple chemokines CCL2, CXCL1, CXCL2, CXCL3, and CXCL8 could act on endothelial cells via VEGFA-KDR/FLT1 and CCL2/CXCLs-ACKR1 interactions, which were crucial for tumor angiogenesis." (PMID 37475874, 2023). "Tumor cells‐secreted CXCL1 and CXCL8 recruit neutrophils and promote activation of ERK and JNK signaling pathways and expression of VEGFA and MMP9 in neutrophils, which induce tumor lymphangiogenesis and facilitate LN metastasis of tumor cells." (PMID 36670069, 2023). "In TNBC, tumor cell-derived conditioned medium induces a polarized morphology and activation of neutrophils, mediated by cytokines such as TGF-β and the ligands for the chemokine receptor CXCR2, i.e., CXCL1/2/3." (PMID 37496019, 2023). "By contrast, CXCL1, CXCL2, CCL2 and TGFB2 with defined pro-tumorigenic roles are more highly expressed by EA1 tumor cells at baseline and may antagonize anti-tumorigenic effects of CD8+ T cells that do infiltrate this model." (PMID 36739466, 2023). "As SMAD4 reduces CXCL1 expression by decreasing inhibitor of NF-κB kinase β (IKKβ) activity and affecting glycogen synthase kinase-3β (GSK-3β), a decrease in SMAD4 expression in a tumor cell increases CXCL1 expression." (PMID 37408240, 2023). "This may be in part due to a multifaceted role of CXCL1 and S100A8/A9 secreted by LL2/B3a tumors in promoting tumor cell proliferation and survival." (PMID 37279067, 2023). "In the subset of tumor-promoting CAFs, iCAFs can participate in immune escape or directly act on pancreatic cancer cells by producing inflammatory cytokines such as IL-6, leukemia inhibitor factor (LIF), and CXCL1 to promote tumor progression." (PMID 37666813, 2023). "Moreover, some cytokines, such as CXCL1/CXCR2 axis, G-CSF, GM-CSF and VEGF-C, have been confirmed to be involved in the recruitment of MDSCs in tumor-bearing mice." (PMID 37268941, 2023).